SIRT2 (sirtuin 2)
Diseases named in the same sentence as SIRT2 in open-access papers (continued):
Sharing a sentence is not in itself a finding about the gene and the disease.
Insulin resistance (continued). "It's worth noting that SIRT1, SIRT2, SIRT3, and SIRT6 are positive regulators of insulin resistance in most cases." (PMID 30559718, 2018). "Insulin resistance is further aggravated in the OBO cohort since SIRT2 suppression no longer inhibits adipogenesis." (PMID 40076884, 2025). "Sirtuin 2 (Sirt2), a NAD-dependent protein deacetylase that participates in deacetylation of histones and other proteins, also contributes to insulin resistance and metabolic syndrome by regulating NLR family pyrin domain containing 3 (NLRP3)-mediated inflammasome activation." (PMID 36499366, 2022). "However, further investigation into the targets and functions of SIRT1, SIRT2, SIRT3, and SIRT6 will aid in the development of new strategies to treat insulin resistance and T2DM." (PMID 30972029, 2019). "SIRT2 gene expression is significantly lower in peripheral blood mononuclear cells of obese children with insulin resistance than in those without insulin resistance." (PMID 30574122, 2018). "We show that SIRT2 KO alone is sufficient to induce muscle insulin resistance in lean mice, and SIRT2 deletion exacerbates diet-induced insulin resistance, independent of a further increase in hyperacetylation." (PMID 30533032, 2018). "The involvement of SIRT2 regulation in inflammation has been extensively reported: SIRT2 deacetylates p65 to regulate the expression of specific NF-κB dependent genes, SIRT2 deacetylates NLRP3 inflammasomes to reverse age-related inflammation and in vitro insulin resistance." (PMID 39226168, 2024). "The results showed that HOMA-IR was negatively correlated with HK2, LDHA, PKM2, SIRT2, and lactic acid levels and had little correlation after RES intervention, which indicated that RES intervention promoted glycolysis by improving ovarian insulin resistance in PCOS rats." (PMID 36742000, 2022). "In contrast, a previous report showed increased body weight and insulin resistance in CD-fed SIRT2-KO mice with no alterations in food intake or energy expenditure, but with increased lean and fat mass, suggesting this explanation for the increased body weight." (PMID 35743232, 2022).
hepatocellular carcinoma (35 papers, 2015 to 2025). A malignant tumor that arises from hepatocytes. "SIRT2 deficiency leads to fibrosis, signaling an adverse outcome in liver disease progression which can be considered as a precursor pathology of cirrhosis and hepatocellular carcinoma." (PMID 39226168, 2024). "This is strongly supported by the ability of SIRT2-knockdown or SIRT2 inhibition, using salermide, to impede the metastasis of hepatocellular carcinoma, gastric cancer, and osteosarcoma cells in xenograft mouse models." (PMID 39682770, 2024). "Studies have indicated a specific increase in the expression of SIRT2 in liver NK cells induced in mice with liver cancer, suggesting that SIRT2 promotes the activity of liver NK cells in response to hepatocellular carcinoma (HCC)." (PMID 38962006, 2024). "The SIRT1 and SIRT2 inhibitors, cambinol and EX-527, were utilized in the context of hepatocellular cancer." (PMID 39479446, 2024). "The human sirtuin 2 gene (SIRT2) encodes a full-length Sirt2 protein (i.e., the Sirt2 isoform 1), which primarily functions as a cytoplasmic α-tubulin deacetylase, and which promotes the growth of hepatocellular carcinoma (HCC)." (PMID 38239506, 2023). "The viral protein HBx can upregulate SIRT2 by targeting its promoter, indicating that SIRT2 promotes hepatitis B virus transcription and replication, thus promoting hepatitis B virus-mediated hepatocellular carcinoma." (PMID 35493297, 2022). "In the specific context of hepatocellular carcinoma, SIRT2 regulates Akt deacetylation and activity, thus promoting glycogen synthase kinase-3β (GSK-3β)/β-catenin signaling and causing EMT and cell migration." (PMID 35745656, 2022). "SIRT2 up‐regulation has been reported in primary hepatocellular carcinoma tumors and correlated with shorter patient survival." (PMID 33400855, 2021). "SIRT2 protein levels are significantly higher in hepatocellular carcinoma specimens, relative to normal liver cells, and expression levels correlate with vascular invasion, advanced tumor stages and shorter survival." (PMID 25915617, 2015). "However, the possible involvement of Sirt2 in the development of hepatocellular carcinoma was determined." (PMID 39004743, 2024). "One animal study showed that Sirtuin2 (SIRT2) could reactivate the anti-tumor activity of depleted NK cells in hepatoma mice." (PMID 34513678, 2021). "We acknowledge that our findings further add to SIRT2’s controversial role considering SIRT2 has been reported to promote the cytotoxic effects of NK cells in hepatocellular carcinoma; however, these studies differ in the types of tumors studied and the approach to SIRT2 expression manipulation." (PMID 34155309, 2021). "However, SIRT2 is also defined as an oncogenic factor associated with cell proliferation and shortened overall survival in pancreatic cancer, hepatocellular carcinoma (HCC), and neuroblastoma." (PMID 31817470, 2019). "Additionally, SIRT2 is an important tumor promoter in hepatocellular cancer." (PMID 39479446, 2024). "Nevertheless, alternative studies have implicated different SIRT2 downstream targets in the regulation of gastric cancer and hepatocellular carcinoma migration, supporting that SIRT2 inhibition may modulate the migratory capacity of different cancer types via diverse mechanisms." (PMID 39682770, 2024). "SIRT2 is upregulated in hepatocellular carcinoma tissues compared to adjacent normal tissues, while migration and invasion of human HCC cells are reduced by knocking down SIRT2." (PMID 35493297, 2022). "Similarly, NK cells overexpressing SIRT2 showed a stronger antitumor effect on hepatoma cells." (PMID 34513678, 2021). "Specifically, miR-150 promotes NSCLC growth via SIRT2/JMJD2A activation, while miR-206 suppresses hepatocellular carcinoma by targeting c-MET." (PMID 41568382, 2025).
hepatocellular carcinoma (continued). "Current strategies for modulating sirtuin activity in the treatment of hepatocellular carcinoma (HCC) and non-alcoholic fatty liver disease (NAFLD) focus on the activation and inhibition of specific sirtuins, particularly SIRT1 and SIRT2, respectively." (PMID 40136715, 2025). "In the realm of hepatocellular carcinoma (HCC), the pharmaceutical sector has investigated the potential of sirtuin-targeting compounds, including the SIRT2 inhibitor salermide." (PMID 40136715, 2025). "Knockdown of SIRT2 in cultured liver cell lines (HepG2 or Huh7) or in HBV infection systems (i.e., HepG2-NTCP or primary human hepatoma) abrogated the levels of cccDNA, pgRNA, sgRNAs, and HBc, core particle assembly, and synthesis of HBV DNA." (PMID 38239506, 2023). "SIRT2 promotes the activity of liver NK cells in response to hepatocellular carcinoma (HCC)." (PMID 34946805, 2021). "Notably, SYVN1 promoted the tumorigenic phenotype by regulating the ubiquitination and degradation of SIRT2 and PTEN in lung cancer and hepatocellular carcinoma." (PMID 37444412, 2023). "In tumours, SIRT2 can be used as a biomarker for the clinical diagnosis and treatment of tumours, such as to predict the development of the epithelial-mesenchymal transition (EMT), hepatocellular carcinoma (HCC), and endometrial cancer (EC)." (PMID 36101744, 2022). "It has been shown that SIRT6 overexpression favors hepatoma cell proliferation through the extracellular signal-regulated kinases 1/2 (ERK1/2) pathway, whereas SIRT2 plays a critical role in promoting HCC metastasis and invasion rather than cell growth by re-routing liver cancer metabolism." (PMID 33920670, 2021). "At the protein level, SIRT2 activates malic enzyme 1 (ME1) activity by deacetylating PGAM5, thereby promoting lipid synthesis and hepatocellular carcinoma (HCC) cell proliferation." (PMID 39930129, 2025).
Alzheimer disease (30 papers, 2011 to 2025). A progressive, neurodegenerative disease characterized by loss of function and death of nerve cells in several areas of the brain leading to loss of cognitive function such as memory and language. "The intronic SNP (rs10410544) in the SIRT2 gene significantly increases risk of Alzheimer's disease." (PMID 28445509, 2017). "Therefore, further investigations are required to clarify the effect of Sirt2 modulators in neuroinflammation associated with Alzheimer’s disease." (PMID 34630044, 2021). "Another polymorphism rs2241703 of SIRT2 was reported to affect Alzheimer’s disease." (PMID 32438712, 2020). "However, only one SNP (rs10410544) located in intron region of SIRT2 might be associated with risk of Alzheimer's disease." (PMID 28514749, 2017). "First, the specific SIRT2 inhibitor AK-1, which is actively being evaluated in Alzheimer’s disease models, was used to inhibit HIV replication in PHA-activated T cells and monocyte-derived macrophages (MDMs) infected in vitro with different HIV strains." (PMID 36719240, 2023). "It was found the level of SIRT2 was increased in the plasma of Alzheimer’s disease (AD) patients than control subjects." (PMID 37215138, 2023). "Elevated levels of SIRT2 have been found in the CSF of a neurodegenerative disease such as Alzheimer’s disease, indicating its potential as a biomarker reflecting CNS damage." (PMID 38203309, 2023). "Recent studies propose SIRT2 pharmacological inhibition as a therapeutic strategy for several neurodegenerative diseases including Alzheimer’s disease (AD)." (PMID 37698780, 2023). "The cytoprotective role of autophagy is known; furthermore, the role of SIRT2 in autophagy in neurological disorders, including Alzheimer’s disease, is also known." (PMID 33810233, 2021). "The first-ranked gene FMR1 was proved to be associated with mental diseases like mental retardation and autism, and five other genes (APP, SNCA, MAPT, SIRT2, APOE) are known to be associated to Alzheimer's disease." (PMID 32038710, 2019). "In this study, javamide-II found in coffee was screened/isolated as a potential Sirt2 inhibitor candidate, possibly utilized for human diseases including Alzheimer's disease and other diseases." (PMID 26986569, 2016). "For answering this question, we are currently preparing to investigate potential effects of the amide on Alzheimer's disease using animal models including Sirt2 knockout mouse." (PMID 26986569, 2016). "We discuss different functions and targets of SIRT1 and SIRT2 in a variety of neurodegenerative diseases including Alzheimer's disease (AD), Parkinson's disease (PD) and Huntington's Disease (HD)." (PMID 23417962, 2013). "And SIRT2 inhibition exhibited neuroprotection in Alzheimer’s disease." (PMID 37215138, 2023). "In addition, SIRT2 inhibition is reported as beneficial in several nervous system disorders, such as Parkinson’s Disease (PD), Alzheimer’s disease (AD), Huntington’s disease (HD), depression, and ischemic stroke." (PMID 37298312, 2023). "Similarly, SIRT2 inhibition in mice alleviates cognitive deficits on mouse models of Alzheimer’s disease, through inhibition of Aβ formation." (PMID 36045741, 2022). "Acetylation of tubulin, a known Sirt2 deacetylation substrate, increases the stability of microtubule, and a reduction of tubulin acetylation in neurons has been reported for individuals with Alzheimer's disease." (PMID 21937767, 2011). "However, the pivotal mechanism of SIRT2 played in Alzheimer's disease (AD) remains unknown." (PMID 32700357, 2020). "On the other hand, SIRT2 expression did not correlate with cognitive performance evaluated in a therapeutic trial targeted at amyloid precursor protein in Alzheimer’s disease." (PMID 39335541, 2024).
Alzheimer disease (continued). "Moreover, they found higher enzymatic activity of SIRT2 in postmortem brain tissue from patients with different neurodegenerative diseases (Parkinson’s disease (PD), PD with dementia, dementia with Lewy bodies (DLB), and Alzheimer’s disease (AD)) compared to control samples." (PMID 33803627, 2021).
Huntington disease (29 papers, 2012 to 2025). Huntington disease (HD) is a rare neurodegenerative disorder of the central nervous system characterized by unwanted choreatic movements, behavioral and psychiatric disturbances and dementia. "SIRT2 protein is highly expressed in brain and spinal cord; its role in inflammation and redox-associated neurodegenerative diseases such as Huntington’s disease and Parkinson’s disease is reported." (PMID 30216989, 2018). "In addition to act as a crucial regulator in neurodevelopment, SIRT2 is also associated with nervous system disorders, in particular, neurodegenerative diseases [Parkinson’s disease (PD), Alzheimer’s disease (AD), and Huntington’s disease (HD)]." (PMID 33014852, 2020). "In contrast, due to its unique inhibition mechanism, the Sirt1 inhibitor EX-527 has nanomolar potency and translational potential in Huntington’s disease but is often used in cellular studies at micromolar concentrations that also inhibit Sirt2." (PMID 38474697, 2024). "AKG2-mediated Sirt2 inhibition also protected against huntingtin-induced toxicity and protein inclusion formation in a primary striatal neuron cell model of Huntington’s disease by decreasing sterol production." (PMID 38474697, 2024). "In Huntington's disease (HD), SIRT2 inhibition was shown to prevent HD by reducing sterol biosynthesis and exerting neuroprotective effects." (PMID 36101744, 2022). "The pharmacological and genetic inhibition of SIRT2 also suppressed pathogenesis in Drosophila and mouse models of Huntington’s disease." (PMID 34943825, 2021). "SIRT2 inhibition is also able to decrease synthesis of sterol and to exert a neuroprotective effect in cellular and rodent models of Huntington’s disease." (PMID 33806509, 2021). "Second, an increase in SIRT2 levels has been described in different neuropsychiatric and neurodegenerative diseases including AD, PD, and Huntington’s disease (HD), both in mouse models and human postmortem brain tissues." (PMID 33803627, 2021). "Protective effects of the AK-1 SIRT2 inhibitor have also been shown in primary neuronal, C. elegans, and Drosophila models of Huntington’s disease (HD)." (PMID 25608039, 2015). "Moreover, earlier studies (2007 and 2010) have demonstrated a positive effect of SIRT2 (genetic or pharmacological) inhibition in Huntington’s disease (HD) and Wallerian degeneration." (PMID 38914873, 2025). "SIRT2 also interferes with autophagy-mediated degradation of protein aggregates in mouse and human cell lines, which likely explains the protective effect against Huntington’s disease." (PMID 33806509, 2021). "SIRT2 appears to play a detrimental role in neurological disorders such as PD, Huntington’s disease and ischemic stroke, and it is important to understand how SIRT2 is regulated since we know little about it." (PMID 31105527, 2019). "However, SIRT2 deficiency did not alter the progression of the disease, raising questions regarding the neuroprotective role of SIRT2 inhibition in Huntington’s disease." (PMID 30216989, 2018). "Genetic knockout of SIRT2 in a Huntington's disease mouse model showed no improvement in tubulin acetylation and the progression of neurological pathologies, whereas treatment with a SIRT2 inhibitor for up to 14 weeks confers neuroprotection against Huntington's related toxicity." (PMID 27070252, 2016).
colorectal cancer (23 papers, 2016 to 2024). A primary or metastatic malignant neoplasm that affects the colon or rectum. "Downregulation of SIRT2 also increases basal autophagy in colorectal cancer cells protecting them from mitotic catastrophe caused by microtubule inhibitors." (PMID 35387119, 2022). "Here, we found that SIRT2 was upregulated in colorectal cancer tissues compared to that in normal samples and that the elevated SIRT2 was associated with poor prognosis in patients with colorectal cancer." (PMID 30584257, 2018). "Hyperacetylation of tubulin stimulated autophagy upon nutrient deprivation, and SIRT2 deficiency increased autophagy in a colorectal cancer cell line." (PMID 28894448, 2017). "The aberrant expression of human sirtuin 2 (SIRT2) has been detected in various types of cancer; however, the biological roles, underlying mechanisms and clinical significance of SIRT2 dysregulation in human colorectal cancer (CRC) remain unclear." (PMID 32697380, 2020). "Increased expression of SIRT2 considerably reduces the proliferation, migration, and invasion of colorectal cancer cells by controlling the acetylation of isocitrate dehydrogenase 1 (IDH1) at the K224." (PMID 39479446, 2024). "Colorectal cancer cell research conducted in 2021 revealed that SIRT2 serves as a direct target gene in the Wnt/β-catenin signaling pathway." (PMID 37175631, 2023). "SIRT2 demonstrated an inhibitory role in cell growth and acted as a tumor suppressor in tumors, especially in colorectal cancer." (PMID 35217651, 2022). "Our previous studies showed IDH1 K224 acetylation, regulated by SIRT2, affected cell metastasis in colorectal cancer." (PMID 34022816, 2021). "Recently, K224 in IDH1 was shown to be deacetylated by SIRT2 to inhibit colorectal cancer and liver metastases." (PMID 34065652, 2021). "And many studies reported that miR-212-5p directly targets SIRT2 and prostaglandin endoperoxide synthase-2 to suppress the proliferation of colorectal cancer cells and protect against ferroptosis-mediated neuronal death." (PMID 34666830, 2021). "SIRT2 importance in colorectal cancer is also assessed by the evidence that a SNP (small nucleotide polymorphism) in 3′-UTR (untranslated) of SIRT2 sequence impeding hsa-miR-376a-5p binding to SIRT2 can increase patient susceptibility to colorectal cancer development." (PMID 35328633, 2022). "Indeed, a recent acetylome analysis in colorectal cancer cells following SIRT2 overexpression and knockdown revealed close to 200 SIRT2 substrates broadly functioning in cytoskeletal organization, metabolic processes, cell cycle regulation, and gene expression." (PMID 37916830, 2023). "Gene Ontology, KEGG, and MetaCore pathway analyses identified SIRT2 substrates involved in diverse pathways, including carbon metabolism, glycolysis, spliceosome, RNA transport, RNA binding, transcription, DNA damage response, the cell cycle, and colorectal cancer." (PMID 35264593, 2022). "Our Gene Ontology, KEGG, and MetaCore pathway analyses identified SIRT2 substrates involved in diverse pathways, including carbon metabolism, glycolysis, the spliceosome, RNA transport, RNA binding, transcription, the DNA damage response, the cell cycle, and colorectal cancer." (PMID 35264593, 2022). "In colorectal cancer (CRC), Wnt/β-catenin inhibition can increase the expression level of the Wnt/β-catenin target gene SIRT2 and promote the proliferation of CRC cells." (PMID 36101744, 2022). "Novel SIRT2 inhibitors potently inhibit tumor growth in a HCT116 xenograft murine model, supporting a role for SIRT2 as a therapeutic target for colorectal cancer." (PMID 35054489, 2022). "Using a label-free quantitative proteomic approach following enrichment for acetylated peptides from SIRT2-depleted and SIRT2-overexpressing HCT116 human colorectal cancer cells, we identified a total of 2,846 unique acetylation sites from 1414 proteins." (PMID 35264593, 2022).